KL (klotho)
Diseases named in the same sentence as KL in open-access papers (continued):
Sharing a sentence is not in itself a finding about the gene and the disease.
Stroke (continued). "Due to the cross-sectional design of the research, we can only establish a correlation between serum klotho levels and the prevalence of stroke, without being able to determine a causal relationship." (PMID 40452763, 2025). "We hypothesize that: Serum klotho concentration inversely correlates with stroke prevalence in adults." (PMID 40452763, 2025). "This could also be the reason why klotho contributes to neuroprotection and the prevention of stroke, and there may exist a potential therapeutic approach." (PMID 40452763, 2025). "In stroke patients, the CSF concentration of irisin was positively correlated with their cognition, and it was also positively correlated with the CSF concentration of klotho." (PMID 34306305, 2021). "This raises the possibility that supplementation with klotho protein may prevent or treat stroke." (PMID 40452763, 2025). "Similarly, the protein Klotho, both in its soluble and EV-associated form, was not proved to be altered in stroke patients compared to CTRL." (PMID 37175644, 2023). "rs650439 appears to affect the onset of stroke via regulation of klotho plasma concentration, although no SNP associated with rs650439 was detected that could modulate transcriptional activity of the klotho gene." (PMID 30595559, 2018). "In the current investigation, data collected from a population of hypertensive patients in the NOAH study were used to assess the association between a polymorphism in the klotho gene and the onset of stroke without the confounding influence of non-hypertensive individuals." (PMID 30595559, 2018). "Univariate logistic analyses revealed significant correlations between Klotho levels and the prevalence of CHF, CHD, heart attack, and stroke (all P < 0.001)." (PMID 35509269, 2022). "In summary, our research indicates a significant negative correlation between serum klotho levels and the prevalence of stroke." (PMID 40452763, 2025). "This study disclosed the negative correlation between serum klotho protein levels and the prevalence of Stroke." (PMID 40452763, 2025). "Finally, through subgroup analysis, we discovered that in the majority of subgroups, the negative correlation between serum klotho levels and the prevalence of stroke was remarkable." (PMID 40452763, 2025). "The antiageing protein Klotho could prolong VSMC survival in the atherosclerotic plaque and delay the consequences of plaque rupture by improving VSMC phenotype to delay heart attacks and stroke." (PMID 35008643, 2021). "Our results show that the serum Klotho concentration is higher in individuals with a clinical history of MI, but not in individuals with a history of CAD or stroke." (PMID 28076518, 2016).
calcification (21 papers, 2012 to 2025). Process by which organic tissue becomes hardened by the physiologic deposit of calcium salts. "By contrast, Klotho was inversely correlated with arterial calcification (r = − 0.388 [− 0.578 to − 0.159], p = 0.001) and CIMT (r = − 0.38 [− 0.53 to − 0.207], p < 0.00001)." (PMID 38459119, 2024). "In contrast to FGF-23, an inverse correlation was found between the Klotho level and arterial calcification [pooled r = − 0.388 (− 0.578 to − 0.159), p = 0.001]." (PMID 38459119, 2024). "The presence of abdominal aortal calcification (P = 0.001) and coronary artery calcification (P = 0.038) were also higher in the low Klotho/FGF23 ratio quartiles." (PMID 35872753, 2022). "Existing studies have shown that malnutrition and microinflammatory state, insulin resistance, FGF23/klotho axis abnormalities, and other factors are interconnected and ultimately jointly promote the occurrence of vascular calcification." (PMID 34367315, 2021). "Klotho influences vascular calcification in CKD and directly inhibits vascular calcification." (PMID 34079811, 2021). "It has been indicated that mice lack Klotho promoted calcification and osteoblastic differentiation of VSMCs, whereas Klotho transgenic mice were observed a significant decrease in the incidence of calcifications and have better preserved renal function compared to wild-type mice with CKD." (PMID 34539972, 2021). "Although the precise mechanism underlying the inhibitory effects of EPA on vascular calcification remains unclear, reduction of NOX activity by EPA might play an important role in prevention of vascular calcification in klotho mutant mice." (PMID 28771600, 2017). "However, the absence of an association between serum calcification inhibitor levels and coronary calcification/arterial stiffness and the fact that MGP and Klotho undergo post-translational modifications underscore the complexity of this association." (PMID 26147960, 2015). "There are two possible reasons why the serum Klotho levels are not significantly correlated with the degree of aortic calcification in human CKD patients." (PMID 23431388, 2013). "This phenomenon may be attributed to the irreversible loss of renal function, CKD exacerbation, elevated serum IS concentrations, decreased Klotho protein levels, and disturbances in calcium, phosphorus, and PTH, ultimately culminating in vascular calcification." (PMID 38385060, 2024).
breast carcinoma (19 papers, 2010 to 2025). "Klotho function as an antiaging protein has been implicated in several types of cancer, notably renal cell carcinoma, gastric cancer, breast cancer, and colorectal cancer." (PMID 41261673, 2025). "Heterozygosity for a certain KL gene variant (KL-VS) is associated with an even higher breast cancer risk of patients with BRCA1 mutation prone to developing breast cancer." (PMID 33520985, 2020). "Compared with serum Klotho in the first tertile, serum Klotho in the second tertile and third tertile were related to a decreased risk of these cancers, except for the breast cancer (p = 0.4468) and the second tertile of digestive cancer [OR (95%CI):0.602 (0.334,1.085)]." (PMID 35841322, 2023). "In cancers such as breast cancer, colorectal cancer, hepatocellular carcinoma, ovarian cancer, and renal cell carcinoma, reduced Klotho expression often correlates with a poor prognosis." (PMID 40004457, 2025). "The normalization of KL expression in breast cancer cells reduces tumor growth, activates tumor suppressor elements, and upregulates the fibroblast growth factor (FGF) signaling pathway, reducing the overall clonogenic proliferation." (PMID 40006994, 2025). "In breast cancer, Klotho overexpression promotes the FGF pathway, further promoting cancer cell growth." (PMID 40004457, 2025). "Elevated expression of KL or the KL1 domain suppressed colony formation in the breast cancer cell lines MCF-7 and MBA-MB-231, while the KL2 domain showed no such effect." (PMID 40004457, 2025). "KL’s tumor suppressive activity was first described in breast cancer, then in other solid tumors such as pancreatic cancer, cervical cancer, and melanoma." (PMID 36833453, 2023). "Forced expression of klotho in breast cancer cells reduced proliferation, whereas klotho silencing resulted in increased proliferation." (PMID 35666743, 2022). "In human breast cancer, klotho is known to suppress tumor growth by inhibiting the IGF-1 pathway and increasing the activation of the FGF pathway." (PMID 35666743, 2022). "Immunohistochemistry analysis of klotho expression in human breast cancer has confirmed significantly reduced staining in malignant breast cancers compared with normal tissues." (PMID 35666743, 2022). "KL overexpression reduces, whereas RNAi-mediated KL down-regulation enhances breast cancer cell proliferation." (PMID 33520985, 2020). "In vitro and ex vivo, methylation of the KL promoter in breast cancer cells is negatively correlated with KL mRNA abundance, suggesting a role of epigenetic silencing of KL in breast cancer." (PMID 33520985, 2020). "Using phosphorylation of ERK1/2 as an indicator for activation of the FGF pathway, the investigators noted stimulation of this pathway in the Klotho transfected breast cancer cells, with inhibition of cellular proliferation." (PMID 32585905, 2020). "Recent investigations elucidated that epigenetic mechanisms, including promoter methylation and histone deacetylation, contributed to the reduced Klotho expression in human breast cancer, cervical cancer, and hepatocellular carcinomas." (PMID 28153033, 2017). "Consistent with previous findings, we found that Klotho is downregulated in breast cancer samples compared to benign controls." (PMID 26556877, 2016). "Here we found that in contrast to the bona fide Klotho proteins, γKlotho is upregulated in breast cancer compared to benign patient-matched tissue." (PMID 26556877, 2016). "Forced expression of Klotho was previously shown to inhibit MCF7 breast cancer cell growth by inhibiting insulin/IGF-1/AKT signaling." (PMID 26556877, 2016). "Klotho is expressed in many tumor types, increasing with progression in ovarian cancer while decreasing in breast cancer." (PMID 25944690, 2015). "Detection of both forms was confirmed with supernatants from cultures of breast cancer cells transfected with membrane-bound, secreted (549 amino acid) or the 980 amino acid extracellular domain of klotho." (PMID 25944690, 2015).
breast carcinoma (continued). "Low KL expression is reported in ductal carcinoma and other invasive forms of breast cancer." (PMID 40006994, 2025). "Furthermore, methylation of KL promoter was identified in five breast cancer cells and a portion of 8 out of 23 breast cancer samples." (PMID 40004457, 2025). "Shmulevich and co-workers suggest that KL is a tumor-suppressor in breast cancer." (PMID 36833453, 2023). "Another study has also confirmed the methylation of the klotho promoter in breast cancer cells and suggested that it may be an early mechanism of tumor development." (PMID 35666743, 2022). "Although the association with klotho expression was evaluated for tumors with sizes >3 cm in diameter, which are known to be associated with mammary tumor malignancy it was not statistically significant." (PMID 35666743, 2022). "Similar to breast cancer, KL might be tumor-suppressing by inhibiting IGF-1R–dependent PI3K/AKT signaling or aerobic glycolysis via ERK/hypoxia-inducible factor 1α (HIF-1α) in CRC." (PMID 33520985, 2020). "In 2008, KL was revealed as a tumor suppressor in breast cancer." (PMID 33520985, 2020). "Also dietary methyltransferase inhibition with green tea polyphenols and histone deacetylase inhibition with sulforaphane up-regulate epigenetically silenced KL in breast cancer cells." (PMID 33520985, 2020). "The tumor suppressive activity of Klotho was first identified in breast cancer in 2008." (PMID 28153033, 2017). "In addition to Klotho, we also found significant downregulation of βKlotho expression in breast cancer specimens." (PMID 26556877, 2016). "While Klotho inhibited IGF-1 and insulin signaling in certain cells, it enhanced DGD signaling in breast cancer cells." (PMID 40004457, 2025). "This study reported that an excessive expression of Klotho minimizes IGF-1R phosphorylation and its downstream targets, such as ERK1 and ERK2, in MCF-7 breast cancer cells." (PMID 40004457, 2025). "Klotho is identified as a potential tumor suppressor and an inhibitor of the IGF-1 pathway and activator of the FGF pathway in human breast cancer." (PMID 23516476, 2013). "Intriguingly, a recently published research suggests that klotho serves as a potential tumor suppressor and identify it as an inhibitor of the IGF-1 pathway and activator of the FGF pathway in human breast cancer." (PMID 20642846, 2010). "Our results consistent with recently published paper which demonstrated that klotho can act as a tumor suppressor and a modulator of the IGF-1 and FGF pathways in human breast cancer." (PMID 20642846, 2010). "Furthermore, KLOTHO promotor methylation was observed in five breast cancer cell lines as well as a proportion (8/23) of breast cancer samples, but not in normal breast samples, suggesting that loss of Klotho expression may be an early event in breast cancer development." (PMID 32585905, 2020). "This suggests that the reduction or absence of KL expression could represent an initial step in the onset of breast cancer." (PMID 40004457, 2025). "In breast cancer, there are significantly lower Klotho levels compared to normal breast tissue." (PMID 40004457, 2025). "Furthermore, HA-tagged Klotho was overexpressed in MCF-7, and MDA-MB-231 breast cancer cells by transfection of pcDNA3 expression vector that resulted in reduced proliferation and a decrease in the number and size of surviving colonies by 84% and 72%, respectively." (PMID 32585905, 2020). "Also, in less-differentiated breast cancer cell lines, KL expression is lower than in the non-tumor breast cell line MCF-12A or in well-differentiated MCF-7 breast cancer cells." (PMID 33520985, 2020). "Apart from KL and PARP4, the 13q linkage peak also includes known candidate genes for inflammation, e.g., arachidonate 5-lipoxygenase-activating protein (ALOX5AP), and cancer, e.g., breast cancer 2 early onset (BRCA2), all of which may be involved in the aging process." (PMID 24036517, 2013).
dementia (19 papers, 2018 to 2025). Loss of intellectual abilities interfering with an individual's social and occupational functions. "There were no reverse associations of genetic liability to other forms of dementia with Klotho concentrations." (PMID 37914711, 2023). "The levels of Klotho level decrease with age, which, in turn, increases the risk of developing dementia." (PMID 37425590, 2023). "This study aimed to investigate the association between Klotho levels and cognitive function and to determine causality between Klotho and dementia using Mendelian randomization (MR)." (PMID 37914711, 2023). "Then, we further evaluated the causal relationship between dementia and Klotho under the framework of the MR analysis." (PMID 37914711, 2023). "Several studies showed a mutation in the Klotho gene or Klotho knockout mice represented the early aging signs such as short lifespan, infertility and dementia." (PMID 33072166, 2020). "Similar findings were found for the risk of Klotho associated with any dementia, VD, FTD and DLB." (PMID 37914711, 2023). "Then, 2-sample MR was conducted to assess the causal relationship between Klotho and dementia." (PMID 37914711, 2023). "Importantly, MR analysis enabled the evaluation of the causal relationship between Klotho and dementia." (PMID 37914711, 2023). "In addition to its association with aging, Klotho is also often related to changes in brain structure, declining cognitive function, and the occurrence of dementia." (PMID 37914711, 2023). "Third, FGF23 may increase the risk of dementia directly through its interaction with klotho, an anti-aging protein." (PMID 30830941, 2019). "Furthermore, we investigated the potential causal relationship between Klotho levels and dementia." (PMID 37914711, 2023). "Considering our recent findings of cognition-related female-specific AD declines in tRF regulators of cholinergic mRNAs26, this suggests links between Klotho-KO-induced transcriptomic perturbations and sex differences in dementia." (PMID 38862813, 2024). "Developing nutritional or pharmacological approaches to boost klotho function warrants investigation for dementia prevention and treatment." (PMID 38505757, 2024). "Several epidemiological studies have assessed the relation of Klotho to cognitive function and dementia." (PMID 37914711, 2023). "The α-KL can be further divided into transmembrane (m-KL), free, and secretory type, with the latter two referred to as soluble KL (s-KL), which is one of the hot spots in current dementia research." (PMID 37214403, 2023). "Median plasma Klotho levels were significantly higher in men than women in the AD-dementia group (men, 871.4 pg/mL [range, 568.7-1027.9 pg/mL]; women, 711.9 pg/mL [range, 568.7-1027.9 pg/mL]; P = .04) but not in the other clinical groups." (PMID 36413367, 2022). "We were unfortunately unable to measure serum klotho levels to determine if this protein modifies the association between serum FGF23 levels and dementia." (PMID 30830941, 2019). "Further research into the links between glucose, klotho and cognition may open promising translational opportunities for dementia prevention." (PMID 38505757, 2024). "Elucidating the role of klotho in neuronal maintenance and resilience may uncover innovative prevention opportunities against cognitive aging and dementia related to metabolic disturbance." (PMID 38505757, 2024). "In the cross-sectional observational study, Klotho and cognitive function were significantly correlated; however, findings from MR studies did not indicate a causal relationship between Klotho and dementia." (PMID 37914711, 2023). "The relationships of Klotho levels with cognition and dementia are poorly understood." (PMID 37914711, 2023). "We found the lowest concentrations of CSF Klotho in individuals with AD-dementia." (PMID 36413367, 2022).
dementia (continued). "Analysis showed significantly lower median CSF Klotho levels in the AD-dementia group compared with the control group among participants younger than 65 years (AD-dementia, 1057 pg/mL [range, 698.18-1411.9 pg/mL]; controls, 1313.1 pg/mL [range 846.5-1726.3 pg/mL]; P = .003)." (PMID 36413367, 2022). "However, the MR analysis results did not support a causal association between Klotho concentrations and dementia risk." (PMID 37914711, 2023). "Human relevance for KL in brain health is supported by studies showing that individuals with elevated KL, due to genetic KLOTHO variation or other reasons, demonstrate better cognition, attenuated neuropathological measures or decreased dementia risk in aging and Alzheimer’s disease." (PMID 37400721, 2023). "It is unclear whether an increase in Klotho levels can prevent dementia at a specific time in life." (PMID 37914711, 2023). "Consequently, no causal relationships between Klotho levels and dementia can be inferred." (PMID 37914711, 2023). "Klotho levels in CSF decreased significantly with age in the control group but not the AD-MCI or AD-dementia groups." (PMID 36413367, 2022). "Within the AD group, the median concentration of Klotho in CSF decreased with disease severity, from 1188.1 pg/mL (range, 756.3-1810.3 pg/mL) in the AD-MCI group to 1073.3 pg/mL (range, 698.2-1661.4 pg/mL) in the AD-dementia group." (PMID 36413367, 2022). "Subgroup analysis showed that CSF Klotho levels were significantly associated with MMSE score in the entire AD group (R2 = 0.048; P = .01) but not the control, AD-MCI, and AD-dementia groups." (PMID 36413367, 2022). "Individuals in the AD-dementia group carrying APOE4 had significantly lower median concentrations of Klotho than noncarriers (APOE4 carriers, 1050.8 pg/mL [range, 698.1-1661.4 pg/mL]; noncarriers, 1378.6 pg/mL [range, 1357.7-1411.0]; P < .001)." (PMID 36413367, 2022). "As a result, based on the present findings, there is no indication that the increase in Klotho levels may be beneficial for the prevention of dementia." (PMID 37914711, 2023). "The significant increase in median Klotho levels was associated with the AD-MCI group (carriers, 936.6 pg/mL [range, 501.7-1563.5 pg/mL]; noncarriers, 790.1 pg/mL [range, 351.9-2733.8 pg/mL]; P = .006) and was not present in the AD-dementia group." (PMID 36413367, 2022).